CASP8 (caspase 8)
Diseases named in the same sentence as CASP8 in open-access papers (continued):
Sharing a sentence is not in itself a finding about the gene and the disease.
tumor (continued). "This class includes genes involved in EMT and caspase 8, whereby loss of caspase 8 function protects tumour cells from programmed death due to release of integrin-regulated anchoring at the invasive front." (PMID 21342498, 2011). "In these experiments, loss of caspase-8 reduced the number of passages required for SV40Tag-induced transformation, as assessed by soft-agar colony formation or tumor formation of cells injected into immune-deficient mice." (PMID 24281211, 2010). "Considering that activation of caspase 8 has been associated with CDDO-induced killing in human tumor cells, it is conceivable that caspase 14 plays a similar role in apoptosis induction in mouse iMycEμ cells." (PMID 16759389, 2006). "In agreement with previous studies reporting a loss of caspase 8 expression in aggressive NBs, in our series a low expression of caspase 8 mRNA was found in all tumours, with a tendency for high risk tumours to express even lower levels." (PMID 16755292, 2006). "The results revealed an increase in KMT2D and CASP8 mutations, which are related to the tumor immune microenvironment, as well as an amplification of chromosome 9p24.1, and deletions of chromosomes 5q12.1, 5q15, and 5q35.3 in the HOXB-AS4 high-expression group." (PMID 40657360, 2025). "This suggests that loss of Caspase-8 is involved in tumor onset." (PMID 39625985, 2024). "Additionally, IFNγ can induce the expression of Fas and caspase-8 genes in tumour cells, rendering them more susceptible to FasL treatment." (PMID 38698968, 2024). "Notably, the mutation frequency of CASP8, closely related to tumour risk, was elevated in the Scissorhigh group, while mutated SYNE1 was mainly occurred in the Scissorlow group." (PMID 37882107, 2024). "As for OV, a study from Ma and colleagues claimed that genetic variants of CASP8 could protect against carcinogenesis and delay tumor onset." (PMID 37120633, 2023). "Accordingly, TNFR1-induced necroptosis typically is only observable when caspase-8 activation is compromised, for example, naturally by genetic alterations in tumor cells or pathogen-encoded factors, such as CrmA or vICA, or artificially by use of drugs or genetic engineering." (PMID 38020877, 2023). "CASP8 mutations could potentially be a self‐defence mechanism in tumours whereby tumour cells resist apoptosis induction by neighbouring FasL overexpressing tumour cells or TILs." (PMID 37443405, 2023). "Our finding of extensive activation of the extrinsic pathway of apoptosis in TILs, together with evidence of higher FasL in CASP8 mutated tumours, may be useful in predicting the course of disease in individual patients." (PMID 37443405, 2023). "Additionally, trabectedin modulates the tumor immune microenvironment by selectively inducing apoptosis of monocytes/macrophages via caspase-8 activation, with an associated reduction in inflammatory cytokines/chemokines and angiogenesis." (PMID 37438818, 2023). "Multiple local administrations of CIMVs-TRAIL into the tumor were associated with the induction of tumor cell death in the CIMV-TRAIL injection group paralleled by remarkable CASP8 activation, which is generally consistent with previous studies on TRAIL antitumor activity." (PMID 36661524, 2023). "Overall, in light of CASP8 exhibiting the highest mutation rate among these PRGs and its observed upregulation in tumor tissues, the detailed etiological role of CASP8 in HNSCC development may warrant further study." (PMID 35123464, 2022). "Inactivation or disturbance of caspase 8 synthesis may cause immortality of damaged cells, which is observed both at the stage of tumor formation and at the stage of progression." (PMID 33800294, 2021). "Additionally, there were high-confidence LoF variants at FANCG and CASP8 in two patients accompanied by somatic loss of heterozygosity in tumor, respectively." (PMID 34285288, 2021).
tumor (continued). "In tumor microenvironment, the tumor-associated macrophages could secret the TNFα, and induce tumor necrosis through the activation of caspase-8, the translocation of PD-L1, and the cleavage of GSDMC." (PMID 34421915, 2021). "Interestingly, the selection pressure on CASP8 in the context of TMD was seen across the entire tumor progression spectrum, while HRAS mutations appeared positively selected specifically in late-stage tumors." (PMID 34307377, 2021). "In addition, autophagic degradation of active caspase-8 has been reported to underlie the resistance of some tumor cells to TRAIL54." (PMID 30718520, 2019). "Interestingly, antioxidants blocked the reduction of tumour growth caused by Vorinostat, but they were unable to inhibit anti-tumoral activity of Vorinostat plus caspase-8 inhibition." (PMID 24651472, 2014). "In addition, we also noted that increased expression of TNF-α and cleaved caspase-8 was associated with the RBM5 overexpression in tumor tissues." (PMID 23721095, 2013). "Several studies have implicated caspase-8 in the migration of tumor cells." (PMID 24281211, 2010). "We considered that selection pressure might result in the loss of caspase-8 DEDs, and increased proliferation and tumor formation might result with continued passage of the cells." (PMID 19924290, 2009). "Knock down of the toxic BH3 domain protein BID, which is downstream of CD95, FADD and pro-caspase 8, significantly reduced the ability of regorafenib alone or in combination with aramchol to cause autophagosome and autolysosome formation and to kill tumor cells." (PMID 40827882, 2025). "In summary, the antitumor effect of Se-PC PDT may address ROS-induced tumor-associated inflammation, and Caspase-8 switches cell death by inhibiting cell proliferation and angiogenesis, diluting cell metabolism and enhancing antioxidant activity and immune capacity in normal tissues." (PMID 37994159, 2023). "Thus, it is possible that caspase-8 could shift the balance between (i) circulating monocytes and differentiated tumor-associated macrophages, (ii) M1 and M2 macrophages, and (iii) anti- and pro-tumorigenic cytokine microenvironment." (PMID 33026575, 2021). "Loss-of-function mutations in CASP8 could lead to reduced apoptosis and promote tumor survival." (PMID 30775178, 2019). "However, given that the functional effect of this polymorphism is largely unknown, the underlying effect on caspase 8 functionality and tumor progression is less clear." (PMID 27507139, 2016). "For example, PTEN and CASP8 act as tumor suppressors, whereas STAT3, MYC, EGFR, and TGFB1 are canonical oncogenic drivers implicated in cell cycle progression, stemness, and therapy resistance, particularly in triple-negative BC." (PMID 41596512, 2026). "Upon analysis, CASP8 expression was found to be significantly higher in tumor tissues than in normal tissues, especially in T cells." (PMID 40149637, 2025). "Caspase-8 activation mediates GSDMD cleavage upon TCR activation, susceptible to suppression by tumor-derived factors." (PMID 40759573, 2025). "Collectively, our results point to a role of the YAP/TAZ-TEAD module in the control of TRAIL-R2/caspase-8 signaling and the cell death response in tumor cells undergoing chronic ER stress." (PMID 39904986, 2025). "Dysregulation of caspase-8 within the tumor microenvironment contributes to inflammation and drug resistance, making it a promising therapeutic target for HCC29,98." (PMID 40555741, 2025). "We also demonstrated that oxidative stress activates CASP8, while STING agonist upregulates IRF1 expression, subsequently inducing ZBP1 and coordinating ZBP1-CASP8 PANoptosome formation in tumor cells." (PMID 40739587, 2025). "BCL11B inhibits caspase-8 activity to block extrinsic apoptosis signaling transduction, consequently enabling tumor cells to evade immune clearance." (PMID 40547036, 2025).
tumor (continued). "FAT1 mutations often disrupt cell adhesion and polarity, promoting oncogenic signaling, while CASP8 alterations can impair apoptotic responses or, conversely, drive pro-inflammatory and pro-survival pathways within the tumor microenvironment." (PMID 41374467, 2025). "Our findings further associate both metabolites with infections, neoplasms, and hyperphagia, showing strong binding affinities to STAT3, HSP90AA1, CASP3, CASP8, and SRC targets." (PMID 41295287, 2025). "EAC tumor progression significantly (p < 0.05) suppressed apoptotic signaling, reducing caspase-8 expression by 63.9% while markedly elevating proliferative STAT-3 levels (+ 668.4%) compared to normal controls." (PMID 41326498, 2025). "Among the pyroptosis-related targets, caspase-3 and caspase-8 require particularly cautious consideration as therapeutic targets, since their activation can yield either anti- or pro-tumor outcomes depending on the downstream pathways engaged." (PMID 41291696, 2025). "In experimental models, the combination of AZD5438 and PD0325901 not only outperformed either monotherapy in suppressing tumor growth but also augmented CD8+ T cell-mediated antitumor immunity by promoting caspase-8/gasdermin E-dependent pyroptosis." (PMID 41194215, 2025). "For caspase-8, high expression of caspase-8 in the nucleus of tumor cells promotes tumor progression, while inhibits tumor growth by acting as a downstream of granzymes, specifically inducing GSDME cleavage." (PMID 40721869, 2025). "TNFAIP8 functions as a negative regulator of cell apoptosis, playing a crucial role in tumor progression by inhibiting caspase activity and leading to the inactivation of caspase-3 and caspase-8." (PMID 40343258, 2025). "This study reports that 4-107, a DBeQ derivative, inhibits VPS4 ATPase activity, induces CASP8-mediated apoptosis, and suppresses tumor growth in mice." (PMID 40147096, 2025). "These compounds can effectively decrease tumour cell survival by activating initiator caspase 3/7, and executive caspase-8 and caspase-9." (PMID 41198778, 2025). "Our results suggest that the local microenvironment of the Casp8-depleted OSCCs resembles a state of chronic inflammation, with barrier malfunction and accumulation of tumor-promoting neutrophils." (PMID 39625985, 2024). "Caspase-8 activity is regulated by phosphorylation; its phosphorylation level is substantially increased in tumor cells to suppress caspase-8 activity, leading to increased resistance to extrinsic apoptosis." (PMID 38200153, 2024). "On one hand, high expression of caspase-8 in the nucleus of tumor cells prevented typical endogenous apoptosis and induced mitosis, thereby promoting tumor progression." (PMID 38553639, 2024). "The dysfunction or reduced activity of Caspase-8 stimulates cellular proliferation, malignant transformation, and tumor progression." (PMID 39272080, 2024). "Analysis of apoptotic pathway in tumor cells by Western blot further revealed that several key proteins, including the cleaved caspase-8, cleaved caspase-3, cleaved PARP, and cytochrome c, were upregulated in the condition of mNK-sEV treatment." (PMID 39075563, 2024).
tumor (continued). "CASP8 was higher in the tumor tissue than in the normal tissue in LUAD, UCEC, COAD, STAD, and GBM; however, it was significantly (p < 0.05) higher in the normal than in the tumor tissue in LUSC patients." (PMID 38542508, 2024). "Radiation treatment significantly inhibited tumor growth in vivo and improved survival in both the control and Casp8 knockdown animal groups." (PMID 39458950, 2024). "For example, the knockdown of DcR3 not only reduces the transcription of cFLIP and caspase-8 but also promotes the differentiation of Th0 cells into Th1 cells, inhibits the differentiation of Th2 and Treg cells, and enhances tumor immunity in HCC." (PMID 39726605, 2024). "Owing to its crucial role in PCD and tumor immunity, targeting caspase-8 presents new opportunities for treating HCC." (PMID 39726605, 2024). "Certain antibiotic chemotherapy agents have been observed to elevate the levels of nPD-L1 and GSDMC while inducing caspase-8, leading to pyroptosis within tumor cells." (PMID 38304430, 2024). "In oncology, CASP8 is recognized as a significant tumor suppressor gene, with aberrant expression or dysfunction linked to the onset, invasion, and metastasis." (PMID 39351539, 2024). "The disruption of lysosome fusion and autophagolysosome formation, along with inhibition of autophagy influx, leads to p62 accumulation, thereby activating caspase-8 and ultimately resulting in tumor cell death." (PMID 38612715, 2024). "Elevated acidity impedes enzymes pivotal for apoptosis initiation, such as caspase-3, caspase-9, and caspase-8, ultimately facilitating cell survival and tumor progression." (PMID 39494260, 2024). "The combination of radiation and birinapant further reduced tumor growth in vivo and provided a survival benefit in both the control and Casp8 knockdown groups." (PMID 39458950, 2024). "Conversely, in tumor cells with low expression of Casp8, PD-L1 is highly expressed, resulting in significant tumor progression." (PMID 39223632, 2024). "This leads to the hypermethylation of tumor suppressor gene promoters, such as hypermethylated in cancer transcriptional repressor 1 (HIC1), RAS association domain family member 1 (RASSF1A), and caspase 8 (CASP8), which results in tumor proliferation." (PMID 39056791, 2024). "Given the key role of Caspase-8 in apoptosis, Casp8 has typically been considered a tumor suppressor gene." (PMID 39625985, 2024). "The PRKCSH-IGF1R axis in tumor cells impairs caspase-8 activation, increases Mcl-1 expression, and inhibits caspase-9, leading to an imbalance between cell death and survival." (PMID 38200153, 2024). "Tumour suppressor genes were under episodic positive selection in most taxa, although this pattern was mostly driven by selection in Casp8 and BRCA2." (PMID 38773187, 2024). "Our findings establish a functional link between epithelial integrity, autophagy, and the tumor immune microenvironment, placing Caspase-8 at the center of these processes." (PMID 39625985, 2024). "Glabridin induces tumor cell apoptosis by upregulating caspase-3, caspase-8, caspase-9 cleavage while enhancing autophagy by upregulating LC3-II and beclin-1." (PMID 39723390, 2024). "Our findings demonstrated that NCAPD3 gene suppressed tumor cell apoptosis through up-regulation anti-apoptotic protein Bcl-2, while down-regulating pro-apoptotic proteins including caspase-8 and Bax, ultimately inactivating the apoptotic cascade in tumors." (PMID 38566039, 2024). "To investigate the contribution of neutrophils to tumor development in our model, we depleted neutrophils by systemic administration of an anti-Ly6G (or an IgG isotype control) in Casp8−/− mice for 8 wk, starting 2 wk after initiation of 4NQO treatment." (PMID 39625985, 2024). "Macrophage TNF-α-driven tumor cell pyroptotic death requires nuclear PD-L1, caspase-8, and GSDMC in vivo." (PMID 39300122, 2024).
tumor (continued). "Tumor sphere size was significantly reduced by TRAIL treatment in PRKCSH-deficient cells, whereas it was restored by treatment with caspase-8 and pan-caspase inhibitors." (PMID 38200153, 2024). "The CASP8 gene expression levels were higher in the tumor tissue than in the normal tissue in LUAD, UCEC, COAD, STAD, and GBM; however, it was higher in the normal than in the tumor tissue in LUSC patients." (PMID 38542508, 2024). "Our data revealed a causative role of Casp8 in modulating the immunogenicity of tumor cells and responsiveness to ICB immunotherapies and proposed radiotherapy as a salvage approach to overcome Casp8 deficiency-mediated ICB resistance." (PMID 36635765, 2023). "SQSTM1 plays an important role in tumor formation by regulating signaling pathways such as the nuclear transcription-related factor 2-antioxidant response, NF-κB and caspase 8-mediated apoptosis pathways." (PMID 37944249, 2023). "Despite the lymphocyte‐rich tumour microenvironment, we observed lower activation of CASP8 (0–10% of tumour area) and its downstream effector CASP3 (0–6%) in tumours than in normal oral epithelium." (PMID 37443405, 2023). "This is understandable, since the impact of Caspase-8 expression appears to be remarkably different based upon tumor context." (PMID 37444381, 2023). "Identical tumor volumes were observed in immunodeficient nude mice, demonstrating no intrinsic difference in the cell growth rates resulting from Casp8 knockout." (PMID 36635765, 2023). "Delving into the influence of CASP8 on the tumor microenvironment of HCC, our research uncovered significant correlations with various immune cell types." (PMID 38186679, 2023). "The correlation between CASP8 expression and tumor immune invasion and immune cell surface indicators was examined using the TIMER and TISIDTISIDB datasets." (PMID 36533709, 2023). "Using Se-PC as a photosensitizer in tumors, pyroptosis was the primary type of tumor death by increasing the activity of Caspase-1 and Caspase-3 and reducing the activity of Caspase-8 and Bcl-2." (PMID 37994159, 2023). "The expression of CASP8 mRNA in tumor tissues was observed to be higher than in the adjacent healthy tissues." (PMID 36533709, 2023). "CASP8 expression is of great relevance to tumor‐infiltrating immune cells in the tumor microenvironment." (PMID 36533709, 2023). "These genes included those related to P/DAMP signaling (e.g., Il6, Tlr1, Tlr4, Il1b, Il18), necroptotic tumor cell death (e.g., Casp1, Casp8, Il1b), and activation of the adaptive immune system (e.g., Cd80, Cd8a, Ccr5, Cxcl10)." (PMID 37213298, 2023). "As per the IHC scores, 18/62 (29.1%) ESCA tumor tissues demonstrated weak CASP8 staining and 44/62 (70.9%) showed strong staining." (PMID 36533709, 2023). "Next, we investigated the TIME role of the tumour suppressor CASP8 whose damaging alterations were predictive of anti-tumour immunity and were enriched in HPV− CNAlow HNSCs." (PMID 37277866, 2023). "In our study, nanoparticle administration significantly increased caspase 8 levels, which also indicates apoptosis as a mechanism of tumor cell death." (PMID 37049344, 2023). "When HINT1 is overexpressed in SW480 and McF-7 tumor cells, it leads to a decrease in Bcl-2 levels, an increase in Bax levels, and elevated expression of caspase-9, caspase-8, and caspase-3, ultimately resulting in the induction of apoptosis in tumor cells." (PMID 38068718, 2023).